RS1 (retinoschisin 1)
Diseases named in the same sentence as RS1 in open-access papers (continued):
Sharing a sentence is not in itself a finding about the gene and the disease.
melanoma (1 paper, 2017). A malignant, usually aggressive tumor composed of atypical, neoplastic melanocytes. "Genes like RS1, APXL or OA1 have been studied in the context of ocular diseases or melanomas, in a way that suggests important functions in melanocyte development." (PMID 28386436, 2017).
multiple myeloma (1 paper, 2025). "PG-SH nanogels modified with TAT-SH have been shown to successfully enable miRNA delivery, mediating gene downregulation in multiple myeloma cells and delivering the antidiabetic peptide RS1-reg to enterocytes in vitro and in vivo (mouse model) after oral administration." (PMID 40715925, 2025).
myopia (1 paper, 2024). "Surprisingly, genes associated with retinal disorders (CLUL1, VSX1, RD3, RS1, and CABP4) and a cone pigment (OPN1LW) were identified in choroid but not retina of progressing chick myopia." (PMID 39028695, 2024).
osteosarcoma (1 paper, 2021). A usually aggressive malignant bone-forming mesenchymal neoplasm, predominantly affecting adolescents and young adults. "RS-1 enhances HDR in HEK-293A and U2OS osteosarcoma cell lines by recruiting RAD51." (PMID 34503562, 2021).
pneumonitis (1 paper, 2022). An inflammatory process affecting the lung parenchyma. "Several of these filtered candidates were found to be secreted (C12orf49, COL10A1, FNDC4, ITLN2, MATN3, PDZD2, RS1, SCRG1, and ST6GALNAC5) making them potential candidate biomarkers useful for distinguishing IPF from pneumonitis." (PMID 35628257, 2022).
Stroke (1 paper, 2020). Sudden impairment of blood flow to a part of the brain due to occlusion or rupture of an artery to the brain. "Besides, we examined cell proliferation following a photothrombotic stroke when the mice received injections of BrdU (i.p., 100 μg/g body weight) 5 days after rS1/9 injection." (PMID 33015039, 2020). "Additionally, we analyzed angiogenesis in the brain after the stroke and rS1/9 administration." (PMID 33015039, 2020).
viral infection (1 paper, 2015). "IE genes, including five members (RL1, UL54, RS1, US1 and US12), are transcribed immediately after viral infection." (PMID 26556803, 2015).
infection (4 papers, 2022 to 2025). The state of being infected such as from the introduction of a foreign agent such as serum, vaccine, antigenic substance or organism. "To identify the RNAs linked to rS1 by ModB during infection by the T4 phage, we developed an RNAylomeSeq approach in which genomically His-tagged rS1 was isolated from T4-infected E. coli and captured on Ni-NTA beads." (PMID 37587340, 2023). "At the earliest stages of infection, only five viral proteins are produced: the IE proteins ICP0, ICP4, ICP22, ICP27, and ICP47, encoded by the genes RL2, RS1, UL1, UL54, and US12, respectively." (PMID 35575489, 2022). "Interestingly, while both CMV-Pa3 and Rs1 belong to subgroup IB, their infection behavior in leguminous hosts differs significantly." (PMID 41373899, 2025).
tumor (1 paper, 2019). "Nine MDV genes and gene products were involved in immune evasion, tumor development and/or pathogenesis, including US1, US10, RLORF4, US3, UL13, RLORF14a, RLORF9, RLORF7, and RS1." (PMID 31921027, 2019).
RS1 also shares sentences with these, for which no sentence is quoted: Macular dystrophy (3 papers); choroideremia (2); Leber hereditary optic neuropathy (2); macular degeneration (2); Norrie disease (2); retinitis pigmentosa (2); albinism (1); deafness (1); early-onset retinal dystrophy (1); ischemia (1); lung adenocarcinoma (1); optic atrophy (1); Photophobia (1); retinal disorder (1); retinal dystrophy (1); vitreous hemorrhage (1).